E2F1 (E2F transcription factor 1)
Diseases named in the same sentence as E2F1 in open-access papers (continued):
Sharing a sentence is not in itself a finding about the gene and the disease.
virus infection (7 papers, 2011 to 2025). "Pathway enrichment analysis informed that E2f1 overexpression upregulated the expression of genes involved in pathways in cancer, cytokines interaction, virus infection, and PI3K-Akt signaling, among others." (PMID 40761766, 2025). "It will be interesting to determine how common the E2F1-mediated DDR is to productive viral infections." (PMID 21589897, 2011). "Although virus infection increases the levels of E2F1, depletion of E2F1 in infected cells reduced its levels approaching that observed in the mock-infected sample." (PMID 21589897, 2011). "Using IPA to examine the genes showing DE mediated by ART in HIV+ cells, we found that ART may decrease viral infection/replication by inhibiting E2F, E2F1, and IFNA2 and by activating let-7, representing upstream regulators." (PMID 32723919, 2020).
asthma (6 papers, 2014 to 2023). "Gene expression studies have linked E2F1 expression levels with childhood and allergic asthma underlying possible implications of this new associated locus in asthma." (PMID 35461280, 2022). "Compared with normal bronchial epithelial cells, E2F1 expression in the lung tissues of asthma patients was different and regulated by c-Myc that regulated cell proliferation and apoptosis." (PMID 37128280, 2023). "E2F1 was differentially expressed in asthma-diagnosed human donor lung tissues compared with normal bronchial epithelial cells." (PMID 24790987, 2014). "NFKB1, STAT6, and E2F1 were the verified asthma-related TFs in PubMed, and they were discovered to exert regulatory impact in this study." (PMID 24790987, 2014). "A complex pathway that could be a future therapeutic target for asthma is the miRNA-106b-5p/E2F1/SIX1." (PMID 37511254, 2023). "By searching PubMed, NFKB1, STAT6, E2F1, USF1, and CBFB were the verified asthma-related TFs, while NFKB1 and STAT6 were the newly discovered asthma-related genes in 2013." (PMID 24790987, 2014). "Accordingly, we speculate that E2F1 may affect the progression and prognosis of various diseases such as asthma, malignant tumor through basal transcriptional regulation of human ADRB2 gene, and that E2F1 may become a new therapeutic target and prognostic marker." (PMID 37128280, 2023).
bladder tumor (6 papers, 2010 to 2020). "Consistently, the BC cell lines T24 and UMUC-3, which exhibit a higher migratory (left) and invasive (right) capacity show significantly elevated E2F1 protein levels compared to RT-4 derived from superficial low-grade bladder tumors." (PMID 31287003, 2019). "Altogether, our results demonstrated that a positive feedback loop comprising FOXD2-AS1, Akt and E2F1 was responsible for FOXD2-AS1-mediated bladder tumor growth and recurrence." (PMID 29445134, 2018). "In the present study, we demonstrated significantly higher expression of both E2F1 and E2F2 in bladder tumor tissues than in non-neoplastic tissues, which are probably due to aberrant transcriptional regulation of KDM5B." (PMID 20226085, 2010).
head and neck cancer (6 papers, 2014 to 2024). A primary or metastatic malignant neoplasm affecting the head and neck. "Klein-Szanto’s study showed that E2F1 gene transfer enhanced the invasion of head and neck carcinoma cells." (PMID 24755270, 2014). "Understanding how to manipulate cell death pathways activated by HPV oncogenes via E2F1 may serve as novel approaches to treat head and neck cancers and other cancers in general." (PMID 26670255, 2015). "A limited number of studies in the literature have investigated the role of E2F1 and E2F2 SNPs in head and neck cancer." (PMID 38360622, 2024). "We observed coincidental high expression of E2F1 and PRMT5 in several tumour types, including pancreatic, colon, and head and neck cancer, with low expression in normal tissue." (PMID 32709847, 2020).
leiomyoma (6 papers, 2007 to 2024). A well-circumscribed benign smooth muscle neoplasm characterized by the presence of spindle cells with cigar-shaped nuclei, interlacing fascicles, and a whorled pattern. "In a recent study, miR-29c, miR-200c, and miR-93 3 were reported to regulate cell proliferation of leiomyoma via their effects on key cell cycle regulatory proteins including E2F transcription factor 1(E2F1), Cyclin D1 (CCND1), and CDK2 in vitro." (PMID 31159158, 2019). "The involvement of many proteins such as FN1, COL1A1, BMP7, CCND1, EZH2, HMGA2, AhR, and E2F1 shown in the protein–protein interaction networks are well known in leiomyoma pathogenesis; others, such as SOX2, REN, PPARG, ABCB1, and NR3C1 are novel and require further investigation." (PMID 36835153, 2023). "Thus, LINC00337 may be involved in the stimulation of cell proliferation in leiomyomas, since leiomyomas express higher levels of E2F1, EZH2, and DNMT1." (PMID 38279317, 2024). "Leiomyomas express these and several other transcription factors that interact with TCF8 including Runx, CITED, EGR1, EGR3, E2F1, Nurr77, c-Myc, Max, and Mad, whose expression is validated in this and our previous study." (PMID 17716379, 2007).
lymph node metastasis (6 papers, 2013 to 2024). "Importantly, in the current study, we show evidence of an association between E2F1/2/7/8 with histological grade, lymph node metastasis, lymph vessel invasion, and deep invasion of cervical stroma." (PMID 33061852, 2020). "This suggests that E2F1 rs3213180, located in 3’UTR, plays a pivotal role in lymph node metastasis, resulting in a more aggressive LSCC phenotype predisposing patients to a higher clinical stage (ST)." (PMID 38360622, 2024). "Our study revealed that the E2F1 rs3213180 GC genotype was significantly related to the development of lymph node metastasis in both univariate and multivariate analyses." (PMID 38360622, 2024). "Although the p value was greater than 0.05, patients with a higher expression level of E2F1 exhibited increased lymph node metastasis and Ki67 positive rate." (PMID 33986804, 2021). "We further analyzed the relationship between E2F1 mRNA expression level and the clinical characteristics of patients, including gender, age, differentiation degree, lymph node metastasis, tumor size, T stage, and Ki67 positive rate." (PMID 33986804, 2021). "Similar to that found for E2F1, upregulated expression of E2F2 was also significantly associated with histological grade (p = 0.003), lymph node metastasis (p = 0.004), lymph vessel invasion (p = 0.014), and invasion depth of cervical stroma (p = 0.002)." (PMID 33061852, 2020). "In our study, E2F1 is upregulated in LSCC specimens, and the E2F1 level is connection with T stage, lymph node metastasis, clinical stage, and prognosis." (PMID 31801947, 2019). "High E2F1 protein level is in connection with clinical stage, T stage, lymph node metastasis, and poor prognosis." (PMID 31801947, 2019). "And the expressions of miR-1205 and E2F1 protein are inversely correlated with LSCC tissues and connected with clinical stage, T stage, lymph node metastasis, and poor prognosis." (PMID 31801947, 2019).
squamous cell carcinoma (6 papers, 2005 to 2025). A carcinoma arising from squamous epithelial cells. "In addition, in A431 human epidermoid carcinoma cells and Chinese hamster ovary cells, E2F1 bound to the MYBL2 promoter and activated its transcription." (PMID 39613162, 2024). "ARID1A interacts with Rb to prevent CDK‐mediated Rb phosphorylation, inhibit E2F transcription factor 1 (E2F1) activity, and subsequently inhibit c‐Myc transcription, revealing a new mechanism of ARID1A in squamous cell carcinoma (SCC)." (PMID 39779467, 2025). "Moreover, we reported that E2F1 and E2F7 were overexpressed in human squamous cell carcinomas approximately 50 fold and 200 fold respectively." (PMID 22272113, 2011).
cardiomyopathy (5 papers, 2017 to 2024). A disease of the heart muscle or myocardium proper. "Of interest, while E2F1 is mainly known to regulate cell cycle progression, it also plays a role in metabolism pathways, whose deregulation is associated with disease, including cardiomyopathies." (PMID 36672271, 2023). "In cardiomyopathy, it has been reported that circ-Foxo3 interacts with anti-senescent proteins ID-1 and E2F1, as well as anti-stress proteins FAK and HIF1α, leading to the relocation of these proteins in cytoplasm." (PMID 38360615, 2024). "Meanwhile, circ-Foxo3 expression level is upregulated in aged patient and mice tissues, overexpression of circ-Foxo3 contributes to the progression of senescence in mice Dox-induced cardiomyopathy cells by interacting with ID1, E2F1, FAK, and HIF1A." (PMID 28219405, 2017).
malignant glioma (5 papers, 2013 to 2021). A grade III or grade IV glioma arising from the central nervous system. "In another study, E2F1 may participate in telomerase activity regulation in malignant glioma cells and its expression seemed to be strongly associated with the survival of patients with malignant brain tumors." (PMID 24023875, 2013). "A correlation between E2F1 and hTERT expression was also detected in the malignant gliomas, indicating that E2F1 regulated hTERT expression via different mechanisms in different cell types." (PMID 27367732, 2016). "Targeting CDCA8 or E2F1 exerted its antitumor effect in malignant glioma." (PMID 33542211, 2021). "The association between miR-10b and E2F1 transcription, observed in TCGA not only in GBM but also in LGG, implies that miR-10b-E2F1-regulated gene expression is important at early stages of cellular transformation toward malignant glioma." (PMID 25738367, 2015).
metastatic disease (5 papers, 2019 to 2025). "High levels of E2F1 have been found in invasive and metastatic tumors, associated with unfavorable patient outcomes." (PMID 39544930, 2024). "The results revealed that the control group exhibited higher expression levels of p-AKT, p-MDM2, and E2F1 in lung metastatic tumors compared to the NCAPD2 knockdown groups." (PMID 41319185, 2025). "Instead E2F1, whose over-expression correlates with unfavorable outcome and metastatic disease, was equally up-regulated in all of the PDXs." (PMID 31216647, 2019). "CDC6, DHFR, E2F1, H2AFZ, MCM2, GUSB and B2M were significantly higher in patients with metastatic disease than in healthy controls, and CDC6, DHFR and E2F1 were significantly higher in metastatic patients than in localized patients." (PMID 37046768, 2023). "As a positive regulator of the E2F1 axis, this information endorses PRMT5 as a viable therapeutic target and further suggests drugs targeting PRMT5 will find clinical utility in metastatic disease." (PMID 32709847, 2020).
papillary thyroid carcinoma (5 papers, 2006 to 2025). "Papillary thyroid carcinoma (PTC) is the most common thyroid neoplasm, whereas transcription factor E2F1 has been previously implicated in PTC progression." (PMID 35592867, 2022). "And RGMB-AS1 was activated via E2F1 and expedited migration and invasion in papillary thyroid carcinoma cells." (PMID 32549756, 2020). "Papillary carcinomas displayed a more complex pattern with a great heterogeneity for p14ARF, p16INK4A expression and an E2F1-independent transcriptional regulation." (PMID 17117177, 2006). "In all histological types, except papillary carcinomas, we observed a statistically significant relationship between p14ARF and E2F1 (r=0.64 to 1, P<0.05)." (PMID 17117177, 2006). "Indeed, such a relationship was observed between p14ARF and E2F1 expression in normal (r=0.41, P=0.01) and tumour tissues (r=0.64 to 1, P<0.05) except for papillary carcinomas (r=0.04, P=0.86)." (PMID 17117177, 2006). "In papillary carcinoma (PTC), CITED1-meditaed interference of p21 and p27 expression can increase the level of phosphorylated Rb and the transcriptional activity of E2F1, which leads to PTC cell proliferation." (PMID 33987018, 2021). "The link between E2F1 and p14ARF expression found in nontumoral thyroid tissue was no more present in papillary carcinomas." (PMID 17117177, 2006). "Strikingly, E2F1 mRNA level was upregulated in all papillary carcinomas, while 45% of them showed a downregulation of p14ARF suggesting that transcriptional regulation of p14ARF in these tumours is independent of E2F1." (PMID 17117177, 2006).
Alzheimer disease (4 papers, 2008 to 2019). A progressive, neurodegenerative disease characterized by loss of function and death of nerve cells in several areas of the brain leading to loss of cognitive function such as memory and language. "Deregulation of cyclin-dependent kinases and abnormal patterns of E2F1 regulation have also been linked with Alzheimer's disease, neurodegeneration, and neuronal apoptosis." (PMID 20405009, 2010).
brain ischemia (4 papers, 2019 to 2026). Diminished or absent blood supply to the brain caused by obstruction (thrombosis or embolism) of an artery resulting in neurologic damage. "Through research, it has been found that E2F1 is involved in biological processes such as cell cycle regulation and apoptosis and plays a certain role in neurodegenerative diseases and ischemic encephalopathy." (PMID 42123587, 2026). "Among them, the target gene neuropilin-1 (NRP1) is a direct target of the transcription factor E2F1 in cerebral ischemia-induced neuronal death." (PMID 33675584, 2021). "Among them, the target gene neuropilin-1 (NRP1) was a direct target of the transcription factor E2F1 in cerebral ischemia-induced neuronal death." (PMID 33675584, 2021). "The E2F1-deficient mice suffer less ischemic damage after 24 h reperfusion, which suggests that E2F1 plays a critical role in promoting cell death in brain ischemia." (PMID 31866820, 2019). "In addition, the absence of E2F1 attenuates ischemic damage in mouse models of focal brain ischemia." (PMID 34439951, 2021).
brain tumors (4 papers, 2020 to 2023). "First, a transgenic mouse model expressing E2F1 in GFAP‐expressing cells (thus including neural precursors) developed brain tumors, including MBs." (PMID 32920979, 2021). "Upregulation of E2F1 has been reported in studies performed both on in vitro and in vivo brain tumor models, which described a significant increase in E2F1 expression levels and activity." (PMID 33430425, 2021). "Furthermore, it is interesting to note that an E2F1 transgenic mouse model was shown to develop brain tumors, including MBs." (PMID 32920979, 2021). "E2F1 has been studied extensively in tumors of the brain and CNS." (PMID 33381564, 2020).
Burkitt lymphoma (4 papers, 2012 to 2022). A rare form of malignant mature B-cell non-Hodgkin lymphoma. "We also treated the EBV-positive Burkitt’s lymphoma (BL) Raji cells and EBV-negative BL41 cells with CAL-101 and we observed a suppression of E2F1 in Raji but with less effect in BL41." (PMID 29235459, 2017).
COVID-19 (4 papers, 2021 to 2024). A disease caused by infection with severe acute respiratory syndrome coronavirus 2. "In COVID-19 interaction, the TF–miRNA network showed that E2F1, MAX, EGR1, YY1, and SRF were the highly expressed TFs, and hsa-miR-19b, hsa-miR-495, hsa-miR-340, hsa-miR-101, and hsa-miR-19a were among significant miRNAs." (PMID 36059456, 2022). "Genes involved in cell cycle, were over-expressed among COVID-19 compared to both HLTY controls and INFL, with a “hill” pattern (e.g. PTTG1, CDC6, MAD2L1, E2F1)." (PMID 34135895, 2021). "In COVID-19 patients, the DEG–miRNA, and DEG–transcription factors (TFs) interactions network analysis revealed that E2F1, MAX, EGR1, YY1, and SRF were the highly expressed TFs, whereas hsa-miR-19b, hsa-miR-495, hsa-miR-340, hsa-miR-101, and hsa-miR-19a were the overexpressed miRNAs." (PMID 36059456, 2022).
cryptorchidism (4 papers, 2016 to 2025). The failure of one or both testes of a male fetus to descend from the abdomen into the scrotum during the late part of pregnancy. "Previous studies have suggested that both overexpression and deletion of E2F1 are implicated in the development of cryptorchidism." (PMID 40486678, 2025). "As cited above, altered E2F1 expression has been significantly associated to several testis disorders such as spermatogenic impairment, cryptorchidism, and TC, particular in those cases of increased gene expression related to supernumerary gene copy numbers." (PMID 31338064, 2019). "Furthermore, copy number variants of E2F1 are associated with cryptorchidism, which indicates that E2F1 plays a role not only in spermatogenesis, but also testicular descent." (PMID 34552771, 2021). "Altogether, these results suggest that the clinical condition associated with abnormal E2F1 expression, due to copy number variation, can be worsened even more by other concomitant environmental conditions, such as heat stress or an history of cryptorchidism, with a likely impact on TC development." (PMID 31338064, 2019). "E2F1 is essential in the progression of cryptorchidism through its regulation of EIF4EBP1 expression." (PMID 40486678, 2025). "Inhibition of E2F1 can effectively reduce apoptosis and excessive autophagy in germ cells of cryptorchidism by downregulating EIF4EBP1 expression, thereby alleviating testicular damage and the decline in fertility in cryptorchidism model mice." (PMID 40486678, 2025). "While E2F1 is known to regulate cell cycle progression, its role in cryptorchidism remains unexplored." (PMID 40486678, 2025). "In this study, we explored the pivotal role of EIF4EBP1 in the pathophysiology of cryptorchidism and examined the regulatory mechanism of its upstream regulator, E2F1." (PMID 40486678, 2025). "To further validate E2F1’s role in cryptorchidism, we inhibited E2F1 in the cryptorchid spermatogonial cell model and assessed its impact on apoptosis and autophagy." (PMID 40486678, 2025). "E2F1 regulates EIF4EBP1 expression in cryptorchidism, contributing to excessive autophagy and apoptosis." (PMID 40486678, 2025). "In summary, this study is the first to elucidate the critical role of EIF4EBP1 in the pathology of cryptorchidism and identify E2F1 as its upstream regulator." (PMID 40486678, 2025). "Inhibiting E2F1 reduces these pathological processes, alleviating testicular damage and improving fertility, highlighting potential therapeutic targets for cryptorchidism." (PMID 40486678, 2025). "This study investigates the role of E2F1 in regulating EIF4EBP1 expression and its contribution to excessive autophagy and apoptosis in cryptorchidism." (PMID 40486678, 2025). "Here, we hypothesize that E2F1-induced upregulation of EIF4EBP1 exacerbates germ cell autophagy and apoptosis, contributing to cryptorchidism pathogenesis." (PMID 40486678, 2025).
diffuse large B-cell lymphoma (4 papers, 2015 to 2022). "This immunohistochemical study was conducted to assess the prognostic role and relationship of SV40 L-TAG and E2F1 in diffuse large B-cell lymphoma (DLBCL) of Egyptian patients." (PMID 26601052, 2015). "It was reported that the cooperation of EZH2 and E2F1 in transcriptional activation is conserved in diffuse large B cell lymphomas, which inspired us to investigate whether such cooperation is conserved across species." (PMID 32093739, 2020).